TPST2 (tyrosylprotein sulfotransferase 2)
Description:
Catalyzes the O-sulfation of tyrosine residues within acidic motifs of polypeptides, using 3'-phosphoadenylyl sulfate (PAPS) as cosubstrate.
Synonyms: TPST-2; TANGO13B
Tractability: Small molecule: a structure with a bound ligand is known; it has a high-quality binding pocket. Antibody: UniProt predicts a signal peptide or a membrane-spanning region. PROTAC: ubiquitination databases record sites on it; its protein half-life has been measured.
Target class: Enzyme; Transferase
Gene: Protein-coding gene on chromosome 22 (26,521,996 to 26,596,717, reverse strand). Ensembl gene ENSG00000128294.
Subcellular location: Golgi apparatus membrane
Pathways (Reactome):
Developmental Biology: Differentiation of naive CD4+ T cells to T helper 1 cells (Th1 cells)
Disease: Defective F8 sulfation at Y1699
Metabolism: Cytosolic sulfonation of small molecules
Metabolism of proteins: Gamma carboxylation, hypusinylation, hydroxylation, and arylsulfatase activation
Gene Ontology:
Molecular function: protein homodimerization activity; protein-tyrosine sulfotransferase activity
Biological process: peptidyl-tyrosine sulfation; 3'-phosphoadenosine 5'-phosphosulfate metabolic process
Cellular component: endoplasmic reticulum; Golgi membrane; Golgi apparatus; Golgi lumen; trans-Golgi network
Genetic constraint (gnomAD): Loss-of-function variants: 16 observed, 25.38 expected, observed/expected ratio (o/e) 0.63, 90% interval 0.43 to 0.96. The upper end of that interval is the gene's LOEUF score, 0.96, which puts it in group 4 of 6, group 1 being the genes least tolerant of losing a copy. Missense variants: 462 observed, 525.09 expected, observed/expected ratio (o/e) 0.88, 90% interval 0.81 to 0.95. Synonymous variants: 229 observed, 225.89 expected, observed/expected ratio (o/e) 1.01, 90% interval 0.91 to 1.13.
Homologues: Orthologues: macaque TPST2 (99% identical), chimpanzee TPST2 (98% identical), guinea pig TPST2 (94% identical), mouse Tpst2 (94% identical), rat Tpst2 (94% identical), dog TPST2 (93% identical), rabbit TPST2 (93% identical), tropical clawed frog tpst2 (74% identical), Drosophila melanogaster Tpst (58% identical), zebrafish tpst2 (57% identical), Caenorhabditis elegans tpst-1 (52% identical), Caenorhabditis elegans tpst-2 (29% identical). Paralogues in human: TPST1 (63% identical).
Diseases named in the same sentence as TPST2 in open-access papers:
TPST2 is named in the same sentence as 31 diseases in open-access papers, as found by Europe PMC text mining. Sharing a sentence is not in itself a finding about the gene and the disease. The quoted sentences say what the papers report.
atherosclerosis (3 papers, 2023 to 2024). A disease characterized by the build-up of fatty material and calcium deposition in the arterial wall resulting in partial or complete occlusion of the arterial lumen. "Knockout of TPST1 and TPST2 decreased atherosclerosis and peritoneal macrophage adherence and migration in CKD condition." (PMID 37424015, 2023). "Notably, the enhanced activity of TPST2 can trigger atherosclerosis via the aggregation of monocytes and macrophages." (PMID 39691718, 2024).
dwarfism (2 papers, 2012 to 2018). "Some of the genes in enriched ontologies are known to have direct effects on growth and size development or even dwarfism: A COMT variant increases the risk of having children with reduced birth weight, knock out of TPST2 or PATZ1 leads to growth retardation in mice." (PMID 30231878, 2018). "Since this modification is indispensable for the activation of TSH signaling, a non-functional TPST2 mutation (Tpst2grt) in DW/J-grt mice leads to congenital hypothyroidism (CH) characterized by severe thyroid hypoplasia and dwarfism related to TSH hyporesponsiveness." (PMID 22299049, 2012).
glioma (2 papers, 2018 to 2024). A benign or malignant brain and spinal cord tumor that arises from glial cells (astrocytes, oligodendrocytes, ependymal cells). "Single-cell RNA sequencing data from public lung cancer and glioma cohorts demonstrated that the expression of TPST2 was negatively correlated with genes associated with antigen presentation, which is one of the representative down-stream targets for IFNγ signaling." (PMID 39095793, 2024). "Similarly, in our analysis of the glioma cohort, we observed that antigen processing and presentation were significantly enriched in TPST2-negative non-immune cells compared to TPST2-positive cells." (PMID 39095793, 2024).
lung carcinoma (2 papers, 2022 to 2024). "For the lung cancer cohort, we initially annotated all clusters based on the most distinct markers for each cluster and confirmed that TPST2 is ubiquitously expressed across multiple cell populations." (PMID 39095793, 2024).
Primary hypothyroidism (2 papers, 2013 to 2016). A type of hypothyroidism that results from a defect in the thyroid gland. "In 2007, it was reported that a Tpst2 gene mutation (C798G) causes autosomal recessive primary hypothyroidism in the growth-retarded grt/grt mouse." (PMID 23951251, 2013). "In a new animal study, tyrosylprotein sulfotransferase-2 knockout mice have salivary hypo function and smaller salivary gland size due to primary hypothyroidism." (PMID 26595829, 2016). "Our findings conclusively demonstrate that low body weight and salivary gland hypofunction in Tpst2-/- mice is due solely to primary hypothyroidism." (PMID 23951251, 2013). "We reported that Tpst2-/- mice have mild-moderate primary hypothyroidism, whereas Tpst1-/- mice are euthyroid." (PMID 23951251, 2013). "In a previous study we showed that Tpst2-/- mice had mild-moderate primary hypothyroidism, whereas Tpst1-/- mice were euthyroid." (PMID 23951251, 2013). "In the Tpst2 knockout, we find both male sterility and primary hypothyroidism, but only very subtle changes in the Tpst1-/- knockout." (PMID 23951251, 2013). "We previously reported that Tpst2-/- mice on a 129S6 genetic background have mild-moderate primary hypothyroidism, whereas Tpst1-/- mice are euthyroid." (PMID 23951251, 2013). "Tpst2-/- mice have mild-moderate primary hypothyroidism, whereas Tpst1-/- mice are euthyroid." (PMID 23951251, 2013). "Our studies demonstrate that Tpst2-/-, but not Tpst1-/- mice, have salivary gland hypofunction and that salivary gland hypofunction is due solely to primary hypothyroidism." (PMID 23951251, 2013).
aortic atherosclerosis (1 paper, 2023). A atherosclerosis that involves the aorta. "Independent of kidney injury, we found that loss of TPST1 and TPST2 decreased aortic atherosclerosis in ApoE−/− mice." (PMID 37424015, 2023).
breast carcinoma (1 paper, 2024). "In breast cancer tissue samples from TCGA, the expression of TPST2 is significantly associated with increased expressions of IFNγ signaling-related genes." (PMID 39095793, 2024). "While these findings may seem contradictory to previous experimental results, they suggest that TPST2 is associated with tumor immunity including IFNγ signaling, and cell cycle regulation in breast cancer tissues." (PMID 39095793, 2024). "Next, we investigated the roles of TPST2 in breast cancer patients by analyzing the transcriptome data." (PMID 39095793, 2024). "The effect of Tpst2 down-regulation on IFNγ responsiveness was also observed in mouse breast cancer 4T1 cells." (PMID 39095793, 2024). "Collectively, these findings indicate that TPST2 exerts inhibitory effects on IFNγ signaling in breast cancer cells." (PMID 39095793, 2024). "Our data demonstrated that TPST2 knockdown enhanced IFNγ signaling in human breast cancer cell lines (MDA-MB-231 and MDA-MB-468) and mouse breast (4T1 and colon (MC38) cancer cell lines." (PMID 39095793, 2024). "The inhibitory role of TPST2 in IFNγ signaling was verified in another breast cancer cell line, MDA-MB-486." (PMID 39095793, 2024).
cardiac arrest (1 paper, 2024). Cessation of breathing and/or cardiac function. "Vitamin B12 may increase the risk of coronary atherosclerosis and cardiovascular death by reducing the levels of VPS29 and PSME1 proteins, while vitamin C may mitigate the risk of cardiac arrest by inhibiting the expression of the TPST2 protein." (PMID 39691718, 2024). "Vitamin C may reduce the risk of cardiac arrest by inhibiting the expression of the TPST2 (Mediated Effect=-0.111, 95% CI:7nbsp;-0.119–-0.103; Mediated Proportion=14.09%, 95% CI: 13.09%-15.09%)." (PMID 39691718, 2024). "Vitamin C, through its regulation of the TPST2 protein, can decrease the risk of cardiac arrest." (PMID 39691718, 2024). "Vitamin C may reduce the risk of cardiac arrest by inhibiting TPST2 expression." (PMID 39691718, 2024).
colon cancer (1 paper, 2024). "We explored the effects of TPST2 knock-down on tumor growth and the host immune system in a syngeneic mouse model using MC38 cells (mouse colon cancer cells), which were reportedly sensitive to anti-PD1 treatment." (PMID 39095793, 2024).
fibrosarcoma (1 paper, 2018). A malignant mesenchymal fibroblastic neoplasm affecting the soft tissue and bone. "By screening the Published Kinase Inhibitor Set, we identified oxindole-based inhibitors of the Ser/Thr kinase RAF (rapidly accelerated fibrosarcoma) as low-micromolar inhibitors of TPST1 and TPST2." (PMID 29934490, 2018).
triple-negative breast carcinoma (1 paper, 2024). An invasive breast carcinoma which is negative for expression of estrogen receptor (ER), progesterone receptor (PR), and human epidermal growth factor receptor 2 (HER2). "Since MDA-MB-231, MDA-MB-468, and 4T1 cells are models for triple-negative breast cancer (TNBC), these findings strongly indicate that TPST2 regulates IFNγ signaling, at least in TNBC." (PMID 39095793, 2024).
cancer (3 papers, 2019 to 2024). A tumor composed of atypical neoplastic, often pleomorphic cells that invade other tissues. "RNA sequencing data revealed TPST2’s inverse correlation with antigen presentation, and increased TPST2 expression is associated with poor prognosis and altered cancer immunity across cancer types." (PMID 39095793, 2024). "These alterations of gene expression by TPST2 highly associated with poor prognosis in certain types of cancers." (PMID 39095793, 2024). "We propose TPST2’s novel role as a suppressor of cancer immunity and advocate for its consideration as a therapeutic target in ICT-based treatments." (PMID 39095793, 2024). "Our data suggest a novel role of TPST2 in cancer immunity and provide an additional strategy for combination therapeutics based on ICT." (PMID 39095793, 2024). "Depletion of TPST2 in cancer cells augmented anti-PD1 antibody efficacy in syngeneic mouse tumor models by enhancing tumor-infiltrating lymphocytes." (PMID 39095793, 2024). "The copy number gains or amplifications of TPST2 gene were observed in several types of cancers, and the mRNA expressions of TPST2 significantly increased compared to normal tissues in several types of tumor tissues (P < 0.05)." (PMID 39095793, 2024). "Our data suggested a novel role of TPST2 in the regulation of cancer immunity, in which TPST2-mediated tyrosine sulfation of IFNGR1 at Y397 constrained IFNγ signaling." (PMID 39095793, 2024). "Copy numbers and gene expression levels of TPST2 significantly increased in several cancer types." (PMID 39095793, 2024). "In addition to roles in the regulation of IFNγ signaling, TPST2 probably plays additional roles in cancer cells." (PMID 39095793, 2024). "In addition, the genes in the hallmarks gene set ‘Apoptosis’ were enriched in TPST2 knock-down cells, which is suggestive of enhanced IFNγ signaling, because IFNγ signaling is known to exert pro-apoptotic effects on cancer cells." (PMID 39095793, 2024). "To identify the tumor intrinsic factors that are associated with responsiveness to cancer immunotherapy, we performed genome-wide CRISPR-Cas9 loss-of-function screens of cancer cells using mice bearing human immune system and identified TPST2 as a therapeutic target to enhance anti-PD1 efficacy." (PMID 39095793, 2024). "In this study, we demonstrated that TPST2 modulates the responsiveness to ICT in cancer cells." (PMID 39095793, 2024). "However, the studies depicting the function of TPST2 in cancer are extremely rare, so that the screen of this gene in our study indicates that its in-depth investigation in LUAD or other cancers should be performed to elucidate its underlying mechanisms." (PMID 35757722, 2022). "Furthermore, we observed copy number gains or amplifications of the TPST2 gene and significantly increased TPST2 mRNA expression in various cancers, with higher TPST2 expression correlating with poorer prognosis in several cancer types, including BRCA, HNSC, OV, SARC, STAD, and UCEC." (PMID 39095793, 2024). "In GSEA, TPST2 knock-down resulted in the depletion of cell cycle-related genes, such as ‘E2F_TARGETS’, ‘G2M_CHECKPOINT’, ‘MYC_TARGETS’, and ‘MITOTIC_SPINDLE’, which is suggestive of enhanced IFNγ signaling, because IFNγ signaling is involved in the anti-proliferative effect on the cancer cells." (PMID 39095793, 2024). "One plausible explanation is that the elevated expression of TPST2 serves as a negative feedback mechanism for cancer immunosuppression in tumors exhibiting heightened IFNγ." (PMID 39095793, 2024). "Tyrosylprotein sulfotransferase-2 (TPST2), known for its role in protein tyrosine O-sulfation, has been suggested to modulate the extracellular protein-protein interactions, but its specific role in cancer immunity remains largely unexplored." (PMID 39095793, 2024).
cancer (continued). "However, the remaining eight cancer-specific DESPGs of GLB1, HSPA5, PDIA3, GNRH1, IFNGR2 ADAM9, TPST2, and TAC4) were not reported in any researches, which could be potential novel prognostic biomarkers in corresponding tumors." (PMID 31824949, 2019).
tumor (2 papers, 2024 to 2025). "Tpst2 knock-down combined with anti-PD1 treatment led to decreased tumor volume and weight versus anti-PD1 monotherapy." (PMID 39095793, 2024). "To further elucidate the mechanistic basis of TPST2 knock-down on enhancing anti-tumor immunity and the efficacy of anti-PD1 therapy, we performed RNA sequencing on residual tumor tissues from syngeneic mouse model." (PMID 39095793, 2024). "We observed a significant increase in effector CD4+ T cells in the tumor-draining lymph nodes, particularly in the group treated with both Tpst2 knock-down and anti-PD1." (PMID 39095793, 2024). "The in vivo effects of TPST2 inhibition were evaluated using mouse syngeneic tumor models and corroborated by bulk and single-cell RNA sequencing analyses." (PMID 39095793, 2024). "Anti-PD1 therapy was found to increase the overall T cell population as a percentage of the total immune cell count within tumor tissues, with a pronounced increase in the Tpst2 knock-down + anti-PD1 group." (PMID 39095793, 2024). "The augmentation of anti-PD1 treatment efficacy by Tpst2 inhibition was confirmed through supplementary independent experiments, validating its impact on tumor reduction and enhancement of immune response." (PMID 39095793, 2024). "Further analysis showed a significant reduction in tumor weight with Tpst2 knock-down and a trend towards decreased tumor weight with the combination treatment." (PMID 39095793, 2024). "TPST2 modulates the tumor immune microenvironment via tyrosine sulfation of interferon gamma receptor 1 (IFNGR1) at residue Y397, attenuating STAT1 signaling, reducing HLA expression and antigen presentation, and consequently diminishing tumor-infiltrating lymphocytes." (PMID 41403951, 2025). "Given TPST2’s known impact on IFN-γ signaling in vitro experiments, we attributed the observed in vivo tumor growth reduction to immune-mediated mechanisms." (PMID 39095793, 2024). "This polarization is crucial for anti-tumor effects and anti-PD1 therapy efficacy, reinforcing the potential of Tpst2 knock-down to boost anti-PD1 treatment outcomes." (PMID 39095793, 2024). "Tpst2 knock-down alone significantly reduced tumor growth and notably enhanced the efficacy of anti-PD1 therapy, suggesting Tpst2 inhibition combined with anti-PD1 as a novel therapeutic strategy in oncology." (PMID 39095793, 2024). "Through cell-cell communication analysis, we examined the interactions between TPST2-negative tumor and non-tumor cells." (PMID 39095793, 2024). "Among the TPST2 negative non-immune cells, 6,743 (46.86%) were tumor cells, and 7,648 (53.14%) were non-tumor cells." (PMID 39095793, 2024). "Further investigating TPST2-negative non-immune cells, we divided them into tumor and non-tumor cells using gene scoring with representative tumor markers." (PMID 39095793, 2024). "This interaction suggests that TPST2-negative tumor cells play a role in immune modulation, potentially enhancing the immune response within the tumor microenvironment." (PMID 39095793, 2024).
infection (1 paper, 2023). The state of being infected such as from the introduction of a foreign agent such as serum, vaccine, antigenic substance or organism. "Having identified that TPST2 promotes the infection and pathogenicity of S. aureus, next, we further investigated whether the TPST2 could accelerate the death of mice infected by S. aureus." (PMID 37671153, 2023). "Furthermore, we found that the survival rates of myeloid TPST2-cko mice infected by control, △HlgACB, and pHlgACB S. aureus strains were significant elevated compared with that of WT mice, which suggests that TPST2 knockout protect mice from infection and lethality by S. aureus." (PMID 37671153, 2023).
TPST2 also shares sentences with these, for which no sentence is quoted: head and neck squamous cell carcinoma (2 papers); breast invasive carcinoma (1); cannabis dependence (1); chronic pancreatitis (1); congenital hypothyroidism (1); coronary atherosclerosis (1); endometrial carcinoma (1); Kidney (1); lymph node metastasis (1); melanoma (1); ovarian serous cystadenocarcinoma (1); periodontitis (1); sarcoma (1); stomach adenocarcinoma (1); Thyroid carcinoma (1); thyroid hypoplasia (1); uterine corpus endometrial carcinoma (1).